CGAS (cyclic GMP-AMP synthase)
Diseases named in the same sentence as CGAS in open-access papers (continued):
Sharing a sentence is not in itself a finding about the gene and the disease.
tumor (continued). "Considering that progressive tumors are generally associated with impaired immune cell activation, coined as “cold” status, the cGAS-STING pathway may become a promising way to “wake up” the tolerant immune cells such as tumor-associated macrophages (TAMs)." (PMID 36879291, 2023). "A possible explanation of this finding may be linked to a different result of the activation of the cGAS-STING pathway in biologically aggressive neoplasms." (PMID 37120444, 2023). "Moreover, tumor cell–intrinsic cGAS/STING activation has been linked to efficient cancer treatment including radiation, chemotherapies, and anti-PD-1/PD-L1 therapies." (PMID 37888903, 2023). "Notably, Pol θ deficiency or inhibition suppressed tumor growth, increased the accumulation of unrepaired DNA damage, and enhanced T cell infiltration via the cGAS/STING pathway." (PMID 37259920, 2023). "Recently, cGAS–STING signal has been hypothesized as a plausible cancer suppressor during the tumor progression by causing genomic instability." (PMID 37051596, 2023). "However, the expression pattern of cGAS-STING in tumor cells and its association with the infiltration of CD8+ T cells, as well as their impact on clinical outcomes, in pMMR/MSS CRC are largely unexplored." (PMID 37345163, 2023). "In addition to directly destroying DNA strands and causing tumor cell death, radiation therapy can activate the cGAS-STING pathway through various mechanisms." (PMID 37153627, 2023). "Thus, the expression levels of cGAS-STING-encoding genes can also be used to predict dMMR tumor response to immunotherapy." (PMID 37153627, 2023). "To investigate whether the activation of cGAS/STING pathway participates in the anti-tumor effect of Trabid deficiency, we treated mice inoculated with Trabid-deficient B16F10 cells with a STING inhibitor C176." (PMID 37237031, 2023). "On the contrary, STING has been intensively investigated for its anti-tumor effects, and it is well documented that exogenous stresses induced DNA damage activates the cGAS/STING pathway, thereby causing upregulation of cytotoxic interferons or infiltrating of T lymphocytes." (PMID 36588690, 2022). "Adding further complexity, combining DNA damaging agents such as radiation with PARPi has potential to enhance the immunogenicity of the tumor cells by promoting neoantigen release, increasing tumor mutational burden, and enhancing immunogenic signaling via the cGAS-STING pathway." (PMID 35118383, 2022). "Through analyzing multiple levels of data from The Cancer Genome Atlas (TCGA), we comprehensively identified the molecular features, its association with tumor-infiltrating immune cells (TIILs), and the clinical relevance of the cGAS-STING pathway across a wide variety of cancer types." (PMID 35983076, 2022). "Furthermore, an excellent study revealed that blockade of phagocytic receptor MERTK on tumor-associated macrophages augmented tumor immunogenicity and potentiated anti-tumor immunity via inducing tumor-cGas and host-STING-dependent type I interferon response." (PMID 35281078, 2022). "Tumours with mutated MMR genes are known to induce cGAS-STING signalling." (PMID 36612217, 2022). "One could hypothesize that SAMHD1, if mutated or downregulated in cancer cells, would lead to accumulating self-DNA that might be sensed through the cGAS-STING pathway thus inducing a tumor-associated chronic inflammatory response." (PMID 34480199, 2022). "The identification of a DNA signature associated with the ability of TEX to activate the cGAS pathway could provide a circulating biomarker of the RT-driven immunogenic tumor response." (PMID 33757523, 2021). "Indeed, experiments using transplantable tumor models in STING- and cGAS-deficient mice revealed that cGAS expression by tumor cells is critical for tumor rejection by NK cells." (PMID 34079557, 2021). "However, some degree of caution should be taken as tumor cell intrinsic cGAS/STING activation has been linked to metastases formation." (PMID 33936033, 2021).
tumor (continued). "Furthermore, we evaluated the function of cGAS by silencing its expression in GC cell lines; and clarified the underlying mechanisms of cGAS-mediated genome instability and tumor development." (PMID 37305397, 2021). "Interestingly, recent studies suggested that DDR defects can increase tumor mutation and neoantigen load as well as cytosolic DNA triggering innate immune response through the cyclic GMP-AMP synthase (cGAS) and STING pathway." (PMID 34680224, 2021). "However, considering that the activation of the cGAS-STING signal pathway is also associated with tumor metastasis, the possible side effects of agonists must be considered when using agonists to treat cancer." (PMID 34956229, 2021). "On the other hand, cGAS–STING axis has also been implicated in tumor metastasis." (PMID 32382015, 2020). "Moreover, radiotherapy can facilitate tumor‐associated antigen release, activation of the cGAS‐STING pathway, and immunogenic cell death." (PMID 32886446, 2020). "However, for cGAS-STING-deficient tumor cells, disabled anti-viral response resulted in rapid virus proliferation and ultimate cell death." (PMID 30935414, 2019). "Conversely, our data suggest that modulation of TNFα or cGAS/STING signaling may allow survival of BRCA-deficient tumor cells, and warrants care in using TNFα antagonists in BRCA mutation carriers." (PMID 30626869, 2019). "In addition, cGAS-STING signaling has been implicated in promoting tumor brain metastasis through gap junction–mediated cGAMP transfer from tumor cells to the astrocytes." (PMID 31601678, 2019). "Moreover, a high level of methylated cGAS was associated with tumor poor outcomes, and K350R or K350M cGAS, in Cgas knockout tumors, cannot rescue tumor growth and immune infiltration with radiotherapy, indicating the pivotal role of K350 methylation on cGAS activity and function." (PMID 40595456, 2025). "Additionally, the increased genomic instability associated with PTEN loss may enhance tumor antigenicity, thereby promoting immune activation via cGAS–STING signaling." (PMID 40650023, 2025). "The anti-tumor activity of monoclonal antibodies may also be linked to the cGAS-STING pathway." (PMID 39464890, 2024). "In addition, activation of the STING pathway augments the antigenicity and recognition of human melanoma cells by tumor-infiltrating lymphocytes (TILs), while loss of STING or cGAS in tumor cells decreases T cell infiltration and response to checkpoint blockade in mismatch repair–deficient tumors." (PMID 38748789, 2024). "Moreover, we highlight the cGAS-STING signaling pathway as a potential mediator of the immune-activated tumor microenvironment in ARID1B-deficient cells, further enhancing our understanding of the complex interplay between genomic alterations and the immune system in cancer." (PMID 38577613, 2024). "In addition to the leaked DNA of tumor cells that are susceptible to genotoxic stress during tumor progression, chemotherapy with platinum drugs, such as cisplatin, can also cause DNA damage and activate the cGAS-STING signaling pathway." (PMID 39170700, 2024). "However, cGAS silencing suppresses the innate immune response and enhances tumor susceptibility." (PMID 38782895, 2024). "In addition, ATR inhibition plays a significant role in the activation of the immune system by increasing the tumor mutational burden and neoantigen load as well as by triggering the accumulation of cytosolic DNA and subsequently inducing the cGAS-STING pathway and the type I IFN response." (PMID 38474014, 2024). "Moreover, the synergistic effects of DOX and REV may enhance tumor-specific adaptive immunity by triggering DNA damage, activating cGAS/STING, and assisting DCs in absorbing tumor-associated antigens from dying tumor cells." (PMID 38868091, 2024).
tumor (continued). "Interestingly, among above reported SLCs and VRACs, tumor LRRC8C expression was most positively correlated with cGAS-STING and vascular normalization-associated genes including vascular stabilization, endothelial-lymphocyte interaction, pericytes and T cell chemotaxis in TCGA database." (PMID 38177099, 2024). "Moreover, cGAS has been implicated in tumor suppression independently of STING." (PMID 38518087, 2024). "Notably, some cancer cells from each tumor origin lack cGas and/or Sting1 and so may be deficient in innate sensing following radiation, consistent with observations in other cancers." (PMID 39622844, 2024). "Moreover, Kaplan–Meier analyses revealed that the tumor cell-intrinsic expression of cGAS-STING tended to be positively associated with 5-year recurrence-free survival (RFS), but not with 10-year overall survival (OS), in patients with pMMR CRC, although these findings were not significant." (PMID 37345163, 2023). "Thus, TRABID deficiency-induced Aurora B destabilization might impede cGAS inactivation in M phase to contribute in part to the anti-tumor immunity." (PMID 37237031, 2023). "In addition, cGAS can promote the apoptosis of tumor cells caused by the cellular mitotic blockade." (PMID 35536585, 2022). "However, whether PARPi-mediated activation of cGAS–STING signaling is dependent on the BRCA mutation status of the tumor is still a matter of debate." (PMID 35326571, 2022). "Notably, loss of cGAS-mediated AIS also impaired the regression of the abscopal tumour." (PMID 36402783, 2022). "Given that the presence of cGAS-STING signaling was strongly correlated with survival in patients with PDAC, we next sought to evaluate whether there is a relationship between the infiltration of tumor-associated immune cells and the presence of cGAS-STING signaling." (PMID 35773436, 2022). "Moreover, in response to various changes and stimuli in the intracellular environment, the cGAS-STING signaling pathway promotes the polarization of tumor-associated macrophages toward the M1 phenotype, thereby secreting inflammatory factors and chemokines to recruit and activate T lymphocytes." (PMID 36231006, 2022). "Hence, further investigation in the context may indicate the predisposition of different cell or cancer types to cGAS/STING mediated anti-tumor immunity." (PMID 29156566, 2017). "It has also been suggested that tumour associated viruses such as human papillomavirus and adenovirus could potentially release oncogenic proteins to block cGAS/STING interactions with tumour suppressors, hence compromising innate immunity and supporting cancer progression." (PMID 28596706, 2017). "In an MC38 syngeneic tumor model, baicalin significantly inhibited tumor growth, reduced HK2 protein levels, activated the cGAS/STING pathway, and promoted a shift in tumor-associated macrophages toward an M1-like polarization state." (PMID 42158859, 2026). "The immune implications of CIN are also critical, with the Cyclic GMP-AMP Synthase-Stimulator of Interferon Genes (cGAS-STING) pathway toggling between anti-tumor immunity and immune evasion." (PMID 42302064, 2026). "To test if cGAS can be activated in ecDNA+ murine tumor cells, we transiently induced cGAS expression with doxycycline." (PMID 41509453, 2026). "Once the tumor is established, persistently activated cGAS-STING pathways have distinct tumor-promoting effects." (PMID 40770563, 2026). "The cyclic guanosine monophosphate (GMP)-adenosine monophosphate (AMP) synthase-stimulator of interferon genes (cGAS-STING) pathway is crucial for tumor immunity." (PMID 41603131, 2026). "When cyclic GAP-AMP synthase (cGAS) senses aberrant cytosolic double-stranded DNA (including tumor-derived DNA), it generates the second messenger cyclic GMP-AMP (cGAMP), which binds to STING on the endoplasmic reticulum membrane." (PMID 41614892, 2026).
tumor (continued). "Special attention is paid to cGAS-STING, immunogenic signaling via damage-associated molecular patterns (DAMPs), and mechanisms that convert a cold tumor into a hot one." (PMID 41799521, 2026). "The expression of cGAS and STING is often suppressed in tumor cells, and reduced expression is associated with poor prognosis and inferior response to immunotherapy." (PMID 40830678, 2026). "The functional significance of the cGAS-STING pathway was investigated through genetic ablation of tumor cells and macrophages." (PMID 41782113, 2026). "Mechanistically, tumor DNA released by cryoablation was taken up by macrophages, activating the cGAS-STING signaling pathway, increasing the pool of CXCL10+ macrophages and CXCL10 secretion." (PMID 41818612, 2026). "5F and Fe2+ can induce ICD in tumor tissues, Mn2+ can initiate the immune response by upregulating the cGAS‐STING signaling pathway, and R848 can further enhance the polarization of macrophages from M2 to M1." (PMID 41114460, 2026). "Immunohistochemical validation in clinical COAD specimens confirmed higher AARS2 protein levels in tumor tissues versus adjacent normal mucosa; concurrent elevation of cGAS protein was observed, though functional activity requires contextual interpretation." (PMID 41836446, 2026). "Chronic activation of the cGAS-STING pathway in some CIN tumor models leads to tumor suppression and increased metastasis in some models." (PMID 41315764, 2026). "Mechanistically, cisplatin-induced DNA damage in tumor cells activated the tumor-intrinsic cGAS-STING pathway, which facilitated the recruitment and activation of CD8+ T cells." (PMID 41782113, 2026). "Preclinical studies have further demonstrated that the pharmacologic or genetic activation of cGAS-STING suppresses tumor growth, promotes dendritic cell maturation, increases effector immune infiltration, and synergizes with PD-1/PD-L1 inhibition." (PMID 42311657, 2026). "It is worth noting that the cGAS-STING pathway activated by mtDNA plays a dual role in tumor immunity." (PMID 41601699, 2026). "By coupling tumor-intrinsic telomere stress with DC-extrinsic checkpoint inhibition, this work establishes a precision platform for cGAS-STING pathway activation, presenting a promising therapeutic strategy for telomerase-positive malignancies." (PMID 41560305, 2026). "CONCLUSIONS: Cabozantinib promotes tumor immunogenicity through mitochondrial disruption and cGAS/STING activation, leading to immune remodeling in HCC." (PMID 41508119, 2026). "In NK cells, mtDNA released by tumor cells partially triggers intrinsic STING activation in NK cells via recognition by cGAS, thereby maintaining the antitumor activity of the TCF-1+ NK cell subset (a subset with long-term memory potential)." (PMID 41601699, 2026). "In this review, we present a new dual-function lipid-based nanovector (LNV) strategy that simultaneously activates the cGAS-STING pathway and induces tumor-associated microglia to repolarize toward the antitumor M1 phenotype." (PMID 42116763, 2026). "Although mRNA LNPs can only target a subset of tumor cells, the cGAS-STING pathway activates cytokines that modulate the tumor immune microenvironment." (PMID 41509453, 2026). "While the roles of the cGAS-STING pathway in tumor immunology have been extensively studied, previous investigations primarily focused on host immune cells in sensing tumor-derived DNA40,41." (PMID 41509453, 2026). "ATP-Mn CNP significantly increased the expression of cGAS-STING-associated genes and activated the corresponding signaling cascades, and thus effectively polarized macrophages from tumor-supportive M2 to antitumor M1 phenotype." (PMID 41716675, 2026). "The released Cu/Mn ions catalyze Fenton-like reaction to induce tumor cell ferroptosis and mitochondrial DNA damage, activating cGAS-STING pathway, and facilitating CD8+ T cells recruitment." (PMID 42035102, 2026).
tumor (continued). "In parallel, we also demonstrate that decitabine, an FDA-approved anti-cancer drug, reactivates endogenous cGAS expression by reversing epigenetic silencing and subsequently elicits anti-tumor activity in ecDNA+ tumors." (PMID 41509453, 2026). "The cGAS-STING pathway plays a central role in controlling tumor progression through nucleic acid sensing and type I Interferon production." (PMID 41501525, 2026). "In summary, our study demonstrates that the Hepa 1-6-mGM-CSF vaccine elicits robust anti-tumour immunity through the coordinated release of ox-mtDNA and GM-CSF, with ox-mtDNA synergistically enhancing immune activation via the cGAS-STING signalling pathway." (PMID 41947668, 2026). "This corresponded with the strongest activation of the cGAS-STING pathway in tumor lysates, as evidenced by maximal expression of p-TBK1, p-IRF3, and IFN-β." (PMID 41356181, 2026). "In recent years, the role of the cGAS-STING pathway in tumor immunity has attracted widespread attention." (PMID 41881950, 2026). "The dsDNA released from the dead tumor cells effectively targets APCs and triggers the cGAS–STING–IFN-I pathway." (PMID 40227734, 2025). "The cytoplasmic deoxyribonucleic acid (DNA) sensor cyclic guanosine monophosphate (GMP) – adenosine monophosphate (AMP) synthase (cGAS) recognizes cytosolic tumor DNA, and then produces 2′3’‐cyclic GMP‐AMP (2′3’‐cGAMP), a natural ligand of the STING protein." (PMID 39488791, 2025). "This interaction not only prevents proper immune activation through the cGAS-STING pathway but also supports tumor survival by inducing protective autophagy, thus contributing to immune evasion and therapeutic resistance." (PMID 40739089, 2025). "This suggests that cGAS‐dependent cGAMP from tumor cells activates STING in γδ T cells and mediates potent tumor immunity during the early stages of tumor development." (PMID 39573933, 2025). "Our initial focus is on the role of cGAS-STING pathway in HCC tumor suppression, exploring how it modifies the tumor immunological environment and ultimately leads to cancer cell clearance." (PMID 40098962, 2025). "In TNBC, the abnormal regulation of the cGAS-STING pathway is closely related to tumor immune evasion and therapeutic drug resistance." (PMID 40567603, 2025). "DNA fragments from both the damaged nucleus and mitochondria activate the cGAS-STING pathway to provoke the anti-tumor immune response." (PMID 40236810, 2025). "The cGAS-STING pathway serves as a crucial mechanism for immune cells to detect tumor-specific antigens." (PMID 40761260, 2025). "In many tumor cells, aberrant DNA accumulation stimulates cGAS-STING signaling, leading to the upregulation of IFN-I and proinflammatory cytokines." (PMID 40282455, 2025). "Deletion of hepatic cGas reduced both basal and oncogene-induced liver injury and tumor development in L-Dnm1l-KO mice." (PMID 41401035, 2025). "The cGAS-STING pathway plays dual roles in promoting both anti-tumor and pro-tumor immunity, which can vary depending on the cancer type and stage." (PMID 40786100, 2025). "In details, tumor cells with chromosomal instability often harbor micronuclei, which chronically activate cGAS-STING and use STING for survival." (PMID 40075527, 2025). "Tumor-derived dsDNA activates the cGAS-STING pathway in APCs, with Mn2+ acting as an effective STING agonist, which induces the secretion of IFN-I and enhances the activation of CTLs." (PMID 41419861, 2025). "cGAS-STING also affects the expression of MHC class I molecules in tumor cells, increasing their recognition by cytotoxic lymphocytes." (PMID 41007722, 2025). "In this study, we performed genomic and transcriptomic analyses of EGFR-mutated NSCLC tumor and cell lines to evaluate the relationship between CIN and the effect of EGFR-TKIs as well as the activity of the intrinsic cGAS–STING signaling pathway." (PMID 40136696, 2025).